ATP8A1 (ATPase phospholipid transporting 8A1)
Description:
Catalytic component of a P4-ATPase flippase complex which catalyzes the hydrolysis of ATP coupled to the transport of aminophospholipids from the outer to the inner leaflet of various membranes and ensures the maintenance of asymmetric distribution of phospholipids. Phospholipid translocation also seems to be implicated in vesicle formation and in uptake of lipid signaling molecules. In vitro, its ATPase activity is selectively and stereospecifically stimulated by phosphatidylserine (PS). The flippase complex ATP8A1:TMEM30A seems to play a role in regulation of cell migration probably involving flippase-mediated translocation of phosphatidylethanolamine (PE) at the cell membrane (By similarity). Acts as aminophospholipid translocase at the cell membrane in neuronal cells (By similarity).
Synonyms: ATPIA; ATPASEII; ATPP2
Tractability: Small molecule: a structure with a bound ligand is known. Antibody: UniProt places it where antibodies can reach, with high confidence; its Gene Ontology location is reachable by antibodies, with high confidence; UniProt predicts a signal peptide or a membrane-spanning region. PROTAC: ubiquitination databases record sites on it; its protein half-life has been measured.
Gene: Protein-coding gene on chromosome 4 (42,408,373 to 42,657,121, reverse strand). Ensembl gene ENSG00000124406.
Subcellular location: Cytoplasmic vesicle, secretory vesicle, chromaffin granule membrane; Cytoplasmic granule; Cell membrane; Endoplasmic reticulum; Golgi apparatus
Subcellular location (Human Protein Atlas): Cytosol; Vesicles
Pathways (Reactome):
Immune System: Neutrophil degranulation
Transport of small molecules: Ion transport by P-type ATPases
Gene Ontology:
Molecular function: ATPase-coupled intramembrane lipid transporter activity; phosphatidylserine flippase activity; phosphatidylserine floppase activity; protein binding; ATPase-coupled monoatomic cation transmembrane transporter activity; ATP binding; ATP hydrolysis activity; magnesium ion binding; nucleotide binding
Biological process: aminophospholipid translocation; monoatomic ion transmembrane transport; phospholipid translocation; transport across blood-brain barrier; monoatomic cation transmembrane transport; phospholipid transport
Cellular component: endoplasmic reticulum; extracellular exosome; Golgi apparatus; membrane; phospholipid-translocating ATPase complex; plasma membrane; azurophil granule membrane; cytoplasmic vesicle; organelle membrane; specific granule membrane; trans-Golgi network; bounding membrane of organelle; chromaffin granule membrane; cytoplasmic vesicle membrane; endomembrane system; secretory vesicle
Genetic constraint (gnomAD): Loss-of-function variants: 58 observed, 109.18 expected, observed/expected ratio (o/e) 0.53, 90% interval 0.43 to 0.66. The upper end of that interval is the gene's LOEUF score, 0.66, which puts it in group 2 of 6, group 1 being the genes least tolerant of losing a copy. Missense variants: 755 observed, 1,038.3 expected, observed/expected ratio (o/e) 0.73, 90% interval 0.68 to 0.77. Synonymous variants: 353 observed, 370.42 expected, observed/expected ratio (o/e) 0.95, 90% interval 0.87 to 1.04.
Homologues: Orthologues: chimpanzee ATP8A1 (99% identical), macaque ATP8A1 (99% identical), mouse Atp8a1 (98% identical), rabbit ATP8A1 (98% identical), dog ATP8A1 (97% identical), guinea pig ATP8A1 (91% identical), pig ATP8A1 (90% identical), tropical clawed frog atp8a1 (87% identical), rat Atp8a1 (82% identical), zebrafish ATP8A1 (46% identical), zebrafish atp8a1 (24% identical), Drosophila melanogaster CG31729 (24% identical), and 2 more. Paralogues in human: ATP8A2 (68% identical), ATP8B1 (40% identical), ATP8B2 (40% identical), ATP8B4 (40% identical), ATP10A (35% identical), ATP10D (35% identical), ATP8B3 (35% identical), ATP10B (34% identical), ATP11B (34% identical), ATP11A (33% identical), ATP11C (33% identical), ATP9B (26% identical), and 1 more.
Diseases named in the same sentence as ATP8A1 in open-access papers:
ATP8A1 is named in the same sentence as 26 diseases in open-access papers, as found by Europe PMC text mining. Sharing a sentence is not in itself a finding about the gene and the disease. The quoted sentences say what the papers report.
non-small cell lung carcinoma (3 papers, 2019 to 2024). A group of at least three distinct histological types of lung cancer, including non-small cell squamous cell carcinoma, adenocarcinoma, and large cell carcinoma. "A role for ATP8A1 in the development and progression of non-small-cell lung cancer (NSCLC) was discovered in a study of the tumor suppressor function of microRNA MiR-140–3p." (PMID 38382846, 2024). "ATP6V1A is known to drive proliferation and invasion in gastric cancer and ATP8A1 in non-small cell lung cancer." (PMID 31338326, 2019). "Also, ATP8A1 was verified to play a role in regulating the growth and mobility of non-small-cell lung cancer cells." (PMID 32900904, 2020).
Ataxia (2 papers, 2018 to 2021). Ataxia refers to impaired coordination of voluntary muscle movement. "We note that murine P4-ATPases ATP8A1 and ATP8A2 are expressed in the nervous system, and knockout mice exhibit deficient hippocampal learning, sensory deficits, cerebellar ataxia, mental retardation, and spinal cord degeneration, and shortened photoreceptor NRE length." (PMID 33759761, 2021). "No ataxia phenotypes were observed in Atp8a1 and Atp8b1 KO mice." (PMID 30185775, 2018).
endometrial cancer (2 papers, 2019 to 2023). Primary or metastatic malignant neoplasm involving the endometrium (mucous membrane that lines the endometrial cavity). "In a study of exome-wide rare variant association with endometrial cancer using germline whole exome data from the MyCode community health initiative, ATP8A1 was identified as one of several candidate genes involved in endometrial cancer predisposition, which could help in personalized prognosis." (PMID 37686603, 2023). "Genome-wide rare variant analysis using the DiscovEHR cohort identified seven genes and one long non-coding RNA to be associated with endometrial cancer, of which two genes RECK and ATP8A1 were replicated (suggestive threshold P < 0.05)." (PMID 31338326, 2019). "Seven genes, including RBM12, NDUFB6, ATP6V1A, RECK, SLC35E1, RFX3 (Bonferroni-corrected P < 0.05) and ATP8A1 (suggestive P < 10−5), and one long non-coding RNA, DLGAP4-AS1 (Bonferroni-corrected P < 0.05), were associated with endometrial cancer." (PMID 31338326, 2019). "Other candidate genes found to be associated with endometrial cancer, ATP6V1A and ATP8A1 act as oncogenes." (PMID 31338326, 2019).
Obesity (2 papers, 2022 to 2024). Accumulation of substantial excess body fat. "In patients with obesity, there was an increased expression of the ATP8A1 gene in visceral adipose tissue." (PMID 38666884, 2024). "Model 3: dependent variable: the expression of ATP8A1; independent variables: obesity, sex, and the gene expression of miR-548b-5p and miR-4643." (PMID 35807162, 2022). "The present study aimed to analyse the effect of sex, obesity, and their interactions on the gene expression of two lipid flippases—ATP8A1 and ATP8B1—and their possible microRNA (miR) modulators in visceral adipose tissue (VAT)." (PMID 35807162, 2022). "Our results showed a marked influence of obesity on the expression of VAT ATP8A1 and ATP8B1, although the effects of obesity were stronger in men than in women, especially for ATP8B1." (PMID 35807162, 2022). "The present study aimed to study the effects of sex, obesity, and their interactions on the gene expression of two P4-ATPases—ATP8A1 and ATP8B1—and their possible miR modulators in VAT." (PMID 35807162, 2022). "An interesting finding is the presence of a significant interaction between obesity and sex in the expression of ATP8A1 and ATP8B1—namely, the stronger effect of obesity increasing the expression of these genes in men than in women." (PMID 35807162, 2022). "Obesity increased ATP8A1 and ATP8B1 gene expression, although this effect was stronger in men than in women." (PMID 35807162, 2022). "In conclusion, our present study delineated the effects of obesity and sex on the gene expression of membrane phospholipid flippases, ATP8A1, and ATP8B1, in VAT." (PMID 35807162, 2022). "The effects of obesity on ATP8A1 and ATP8B1 gene expression levels in VAT were sex-dependent, according to which higher effects were observed in men." (PMID 35807162, 2022). "Regression models supported a positive influence of obesity on the expression of ATP8A1 and ATP8B1." (PMID 35807162, 2022). "The first regression model (R2 = 0.240, F = 6.9, p = 0.015) suggested that 24% of the variation in the expression of ATP8A1 could be explained by a positive effect of obesity (ß = 0.490, p = 0.015)." (PMID 35807162, 2022). "Our results showed a marked influence of obesity on VAT ATP8A1 and ATP8B1, although the effects of obesity were stronger in men for ATP8A1." (PMID 35807162, 2022). "The present study is the first study to analyse ATP8A1 and ATP8B1 in adipose tissue and to evaluate the effect of obesity and sex on their gene expression levels." (PMID 35807162, 2022). "Obesity significantly increased the expression of ATP8A1 and ATP8B1 irrespective of sex." (PMID 35807162, 2022).
viral infection (2 papers, 2009 to 2024). "The function for four targets have been ascribed (ROBO1, NLGN1, CPSF1, ATP8A1), but none of them have been linked with viral infection." (PMID 19788744, 2009).
autism spectrum disorder (1 paper, 2022). A spectrum of developmental disorders that includes autism, and Asperger syndrome. "There were de novo variants that lacked phenotypic consistency; a splicing site variant of ATP8A1 was detected in a patient with autism spectrum disorder and delayed development who did not have any symptoms and signs related to cholestasis." (PMID 36619507, 2022).
breast carcinoma (1 paper, 2023). "Cohort data available from the Cancer Genome Atlas showed that high expression of PPP1R12A, PP1B encoding the catalytic subunit of the myosin phosphatase complex, or ATP8A1 correlated with poor prognosis in breast cancer patients." (PMID 37957190, 2023). "Cohort data available from TCGA showed that high expression of PPP1R12A, PP1B, or ATP8A1 correlated with poor prognosis in breast cancer patients." (PMID 37957190, 2023). "Combined with the present results using MDA-MB-231 cells, the active “ATP8A1-PS-YAP phosphatase (PPP1R12A/PP1B)” axis may account for the poor prognosis of breast cancer patients through YAP activation." (PMID 37957190, 2023). "Kaplan–Meier survival curves from TCGA cohort data indicated that high expression of ATP8A1, PPP1R12A, or PP1B correlated with shorter overall survival periods for breast cancer patients." (PMID 37957190, 2023). "Therefore, we sought to ask whether ATP8A1, PPP1R12A, or PP1B, which we suggested as YAP-activating factors in the previous and the present study, was related to the prognosis of breast cancer patients." (PMID 37957190, 2023).
head and neck cancer (1 paper, 2024). A primary or metastatic malignant neoplasm affecting the head and neck. "We then hypothesised that the 5 upregulated genes (namely, ATPase phospholipid transporting 8A1 [ATP8A1], BAHD1, cathepsin [CTSD], janus kinase 1 [JAK1], and myosin regulatory light chain interacting protein [MYLIP]) play a role in radioresistance of prostate and head and neck cancers." (PMID 39719436, 2024).
lung carcinoma (1 paper, 2021). "For example, miR-140-3p is a tumor suppressor in lung cancer, which can restrain the multiplication and invasion of lung cancer cells by targeting ATP8A1; miR-140-3p enhances the sensitivity of HCC cells to sorafenib via targeting pregnenolone X receptor." (PMID 34002672, 2021).
lung fibrosis (1 paper, 2023). "Conversely, genetic AP-3 loss in alveolar type 2 epithelial cells and the pearl mouse model caused ATP8A1 retention in REs and concomitant accumulation of PS in the RE membrane and YAP activation, which may underlie progressive lung fibrosis associated with Hermansky-Pudlak syndrome type 2." (PMID 37957190, 2023).
metastatic cancer (1 paper, 2017). A carcinoma which has spread from the original site of growth to another anatomic site. "The proliferation of YAP-dependent metastatic cancer cells is suppressed by knockdown of ATP8A1 or evectin-2." (PMID 29093443, 2017).
neuroblastoma (1 paper, 2012). Neuroblastoma (NB) is the most common solid, extracranial childhood tumor. "ATP8A1 is implicated in the exposure of PS in the outer leaflet of the plasma membrane of neuroblastoma cells, this alteration of surface lipid components leading to phagocytosis of cancer cells." (PMID 23482333, 2012).
progressive familial intrahepatic cholestasis (1 paper, 2024). Progressive familial intrahepatic cholestasis (PFIC) refers to a heterogeneous group of autosomal recessive disorders of childhood that disrupt bile formation and present with cholestasis of hepatocellular origin. "Patients with ATP8B1 mutations causing progressive familial intrahepatic cholestasis (PFIC) appear to be susceptible to pneumonia, and mice homozygous for the Atp8a1-G308V PFIC mutation were more sensitive to bacteria-induced lung injury." (PMID 38382846, 2024).
pulmonary hypertension (1 paper, 2025). Increased pressure within the pulmonary circulation due to lung or heart disorder. "Currently, no research on the relationship between ATP8A1 and pulmonary hypertension has been found." (PMID 40357364, 2025).
Sepsis (1 paper, 2025). Sepsis is defined as life-threatening organ dysfunction caused by a dysregulated host response to infection. "SNP rs189940971 reported via this study was found in gene ATP8A1, which is expressed at higher levels in sepsis patients and involved in several functions related to lipid transport." (PMID 40011956, 2025).
cancer (6 papers, 2011 to 2024). A tumor composed of atypical neoplastic, often pleomorphic cells that invade other tissues. "Three variants in RBM12, one variant in NDUFB6, ten variants in DLGAP4-AS1, five variants in ATPV1A, eleven variants in RECK, four variants in SLC35E1, eight variants in RFX3, and eight variants in ATP8A1 were known somatically acquired mutations in various cancers." (PMID 31338326, 2019). "Increased ATP8A1 expression is associated with invasiveness and metastasis in non-small lung cancer (NSLC), and ATP8A1 knockdown decreased the invasiveness of NSCL cancer cells in vitro." (PMID 37749499, 2023). "In cancer, miR-140-3p usually acts as cancer suppressor, such as suppressing cell growth in colorectal cancer by PD-L1, suppressing growth and invasion of cell lung cancer by down-regulating ATP8A1, and inhibiting progression of cutaneous melanoma by targeting ABHD2." (PMID 35120526, 2022).
tumor (6 papers, 2017 to 2024). "Conversely, among the MDGs, low expression of ATP8A1 was commonly associated with tumor grades (G2 and G3) and unfavorable clinical outcomes (treatment response-PD, SD, and post-treatment outcome-RP)." (PMID 38741142, 2024). "Our results indicate that TMEM30A and ATP11A promote the migration of tumor cells, which is consistent with reports that depletion of either TMEM30A or ATP8A1 causes a severe defect in cell migration." (PMID 28640862, 2017). "In a study of 25 cases of tumor tissues and the adjacent normal tissues from surgeries of NSCLC patients, ATP8A1 was found to be overexpressed in NSCLC tissues by immunohistochemical staining." (PMID 38382846, 2024). "The role of ATP8A1 in the development and progression of non-small-cell lung cancer (NSCLC) was discovered in a study of the tumor suppressor function of microRNA MiR-140-3p." (PMID 37686603, 2023). "In a study of 25 cases of tumor tissues and the adjacent normal tissues from surgeries of NSCLC patients, ATP8A1 was found overexpressed in NSCLC tissues by immunohistochemical staining." (PMID 37686603, 2023).
ATP8A1 also shares sentences with these, for which no sentence is quoted: infection (2 papers); cerebellar ataxia (1); cholestasis (1); diabetes (1); gastric cancer (1); Insulin resistance (1); metabolic disorders (1); metabolic syndrome (1); nematode infection (1).